DIO1 (iodothyronine deiodinase 1)
Description:
Plays a crucial role in the metabolism of thyroid hormones (TH) and has specific roles in TH activation and inactivation by deiodination. Catalyzes the deiodination of L-thyroxine (T4) to 3,5,3'-triiodothyronine (T3), 3,3',5'-triiodothyronine (rT3) to 3,3'-diiodothyronine (3,3'-T2) and 3',5'-diiodothyronine (3',5'-T2) to 3'-monoiodothyronine (3'-T1) via outer-ring deiodination (ORD). Catalyzes the deiodination of T4 to 3,3',5'-triiodothyronine (rT3) via inner-ring deiodination (IRD). Catalyzes the deiodination of T3 to 3,3'-T2, 3,5-diiodothyronine (3,5-T2) to 3-monoiodothyronine (3-T1) and 3,3'-T2 to 3-T1 via IRD (By similarity). Catalyzes the phenolic ring deiodinations of 3,3',5'-triiodothyronamine and 3',5'-diiodothyronamine. Catalyzes the phenolic ring deiodination of 3,3'-diiodothyronamine and tyrosyl ring deiodinations of 3,5,3'-triiodothyronamine and 3,5-diiodothyronamine (By similarity). Catalyzes the deiodination of L-thyroxine sulfate and 3,3',5-triiodo-L-thyronine sulfate via IRD and of 3,3',5'-triiodo-L-thyronine sulfate via ORD (By similarity).
Synonyms: TXDI1; 5DI; THMA2
Tractability: Small molecule: an approved drug acts on it; it belongs to a druggable protein family. Antibody: its Gene Ontology location is reachable by antibodies, with high confidence; UniProt places it where antibodies can reach, with medium confidence; UniProt predicts a signal peptide or a membrane-spanning region.
Target class: Enzyme; Oxidoreductase
Safety:
Unwanted effects reported when the protein is acted on. In parentheses: how it was acted on, where the effect was seen, and who reports it.
Decrease, Population growth rate (inhibition; source: AOP-Wiki)
Increased Mortality (inhibition; source: AOP-Wiki)
Altered, Amphibian metamorphosis (inhibition; source: AOP-Wiki)
Gene: Protein-coding gene on chromosome 1 (53,891,239 to 53,911,086, forward strand). Ensembl gene ENSG00000211452.
Subcellular location: Cell membrane; Endoplasmic reticulum membrane; Basolateral cell membrane
Pathways (Reactome):
Metabolism: Regulation of thyroid hormone activity
Gene Ontology:
Molecular function: thyroxine 5'-deiodinase activity; thyroxine 5-deiodinase activity; selenium binding
Biological process: amino acid metabolic process; thyroid hormone catabolic process; thyroid hormone generation; thyroid hormone metabolic process
Cellular component: basolateral plasma membrane; endoplasmic reticulum membrane; plasma membrane
Genetic constraint (gnomAD): Loss-of-function variants: 17 observed, 27.6 expected, observed/expected ratio (o/e) 0.62, 90% interval 0.42 to 0.92. The upper end of that interval is the gene's LOEUF score, 0.92, which puts it in group 3 of 6, group 1 being the genes least tolerant of losing a copy. Missense variants: 270 observed, 327.86 expected, observed/expected ratio (o/e) 0.82, 90% interval 0.75 to 0.91. Synonymous variants: 115 observed, 120.4 expected, observed/expected ratio (o/e) 0.96, 90% interval 0.82 to 1.12.
Homologues: Orthologues: chimpanzee DIO1 (98% identical), macaque DIO1 (96% identical), pig DIO1 (86% identical), rabbit DIO1 (84% identical), dog DIO1 (81% identical), rat Dio1 (81% identical), mouse Dio1 (79% identical), guinea pig DIO1 (77% identical), tropical clawed frog dio1 (30% identical). Paralogues in human: DIO2 (36% identical), DIO3 (36% identical).
Diseases named in the same sentence as DIO1 in open-access papers:
DIO1 is named in the same sentence as 58 diseases in open-access papers, as found by Europe PMC text mining. Sharing a sentence is not in itself a finding about the gene and the disease. The quoted sentences say what the papers report.
hypothyroidism (18 papers, 2011 to 2025). Abnormally low levels of thyroid hormone. "In case of a specific genetic variant, namely genotype CC in polymorphism rs2235544 of gene DIO1, the simulation results suggest that the L-T4 monotherapy is better to treat hypothyroidism." (PMID 35813623, 2022). "Differently from mice, the detected hypothyroidism has been suggested by the inhibition of Dio3 transcripts beyond the increment of Dio1 and Dio2 mRNAs." (PMID 36769379, 2023). "Local hypothyroidism is consistent with the differential expression of pancreatic deiodinases: low Dio1 (0.3 ± 0.07 vs. 1.4 ± 0.2) and high Dio3 (2.4 ± 0.7 vs. 0.8 ± 0.2)." (PMID 37834351, 2023). "Iodothyronine deiodinase 1 (DIO1) also plays a role in cardiovascular health: a change in circulating lipoproteins occurs in case of hypothyroidism, with an increase of the atherogenic features." (PMID 35204134, 2022). "Albeit hypothyroidism is reflected (acutely) by altered tissue enzyme activities of Dio1 and Dehal1 in both age groups, iodine depletion in the thyroid tissue was less severe in elderly mice." (PMID 35387426, 2022). "Thyroidal increase of Dio1 and Dehal1 are in line with the literature on effects of hypothyroidism in rodent models." (PMID 34836027, 2021). "It was demonstrated that hypothyroidism was related to the increase of dio2 and/or dio1 mRNA expression, when zebrafish larvae were exposed to other environmental pollutants." (PMID 28467477, 2017). "In this study, both Dio1 and Dio2 were significantly induced after MEHP exposure, consistent with previous study demonstrating that hypothyroidism increases Dio1 and Dio2 activities and mRNA expression." (PMID 24658602, 2014). "Oxidative stress and ROS, such as H2O2, can oxidatively damage the selenocysteine active site of DIO1, suppressing DIO1 gene expression and enzymatic activity, thus reducing T3 synthesis, a pattern consistent with subclinical or compensatory hypothyroidism." (PMID 41002415, 2025). "Indeed, we found an upregulation of deiodinase 1 (Dio1) mRNA, concomitantly with a decrease of liver fT3 level, suggesting a condition of hypothyroidism in CPF exposed F2 mouse livers." (PMID 37298533, 2023). "These hormonal changes, however, did not result in tissue hypothyroidism, in liver or brain, with normal expression of Dio1 and Hr, respectively." (PMID 24819605, 2014). "Moreover, at least other two up-regulated miRs - miR-421-3p and miR-185-5p - are also predicted (Target Scan), but not experimentally validated, to target Dio1, further supporting the notion that local hypothyroidism can favour progression to HCC." (PMID 36203462, 2022). "We found that late gestation pig fetuses experiencing hypothyroidism but had no signs of compromise, showed decreased DIO1 expression in the liver, which could result in a local suppression of T4 conversion to active and inactive forms due to the dual activity of the enzyme." (PMID 36175938, 2022). "In late gestation, DIO1 is known to be downregulated in the fetal LVR, but not the fetal KID, in response to hypothyroidism, which could help to explain the differential sensitivity of fetal tissues to thyroid hormones." (PMID 40693299, 2025).
hyperthyroidism (9 papers, 2016 to 2024). Overactivity of the thyroid gland resulting in overproduction of thyroid hormone and increased metabolic rate. "In mice, hyperthyroidism leads to increased expression of Dio1 in the kidney as well as Dio1 and Spot14 in the liver, both TH-responsive genes." (PMID 38567302, 2024). "Whereas Dio2 activity is inversely related to fT4 concentration due to substrate-induced ubiquitination of the enzyme, Dio1 activity increased during hyperthyroidism." (PMID 36892852, 2023). "This may indicate that although Dio1 contributes to a greater extent to the T3 production in hyperthyroidism, Dio1 also increases T3 clearance and is thus beneficial in maintaining serum T3 concentrations within normal limits in the hyperthyroid state." (PMID 36892852, 2023). "This may be due to enhanced deiodination from T4 to T3 through DIO1 in patients with Graves' hyperthyroidism and our data suggest that the DIO1 is activated in Graves' hyperthyroidism." (PMID 36565031, 2023). "However, the observed upregulation of Dio1 in the liver on 3,5-T2 treatment is similar to the upregulation of Dio1, typically observed upon TH-induced hyperthyroidism." (PMID 35888706, 2022). "An indirect method using propylthiouracil (PTU) in that study showed that DIO1-generated T3 in the thyroid gland was the major source of plasma T3 in patients with hyperthyroidism since PTU could inhibit DIO1." (PMID 29971103, 2018). "Thus, a higher expression of TH-responsive genes Dio1 and Me1 was noted in hyperthyroidism in female mice liver, and Tbg transcripts were elevated in hypothyroid female liver compared to male mice." (PMID 27559466, 2016). "In future experiments, it will be interesting to further investigate the role of liver Dio1 on T3 in stressed conditions such as hyperthyroidism and fasting/feeding conditions to investigate whether Dio1 contributes to local liver T3 production in these states." (PMID 36892852, 2023). "This increased production of T3 by Dio1 in hyperthyroidism has always been intriguing as it does not fit the classic feedback mechanism." (PMID 36892852, 2023). "Thus, the enhanced hepatic Dio1 activity along with altered serum TH concentrations and pituitary transcripts on 3,5-T2 treatment are indicative of a local hyperthyroidism accompanied by accumulation of hepatic 3,5-T2, which apparently is not deiodinated by high Dio1 activity." (PMID 35888706, 2022).
breast carcinoma (6 papers, 2011 to 2023). "Moreover, an overexpression of DIO1 was found in breast cancer tissues and associated with advanced stages." (PMID 35158912, 2022). "Although insignificant at the GWAS level, one SNP in the DIO1 gene has been associated with both free T4 and breast cancer, suggesting the role of deiodinase activity in the association between thyroid function and breast cancer." (PMID 32838791, 2020). "Conversely, in breast cancer, miR-383 is lost while DIO1 expression significantly increases." (PMID 21912701, 2011). "Treatment of breast cancer cells with iodine/iodide results in upregulation of ACR1C1 and SLC7A5, the two genes that were upregulated by DIO1 overexpression in our study." (PMID 29272308, 2017). "Overall, considering both the CCLE and LINCS datasets, eight selenoproteins were overexpressed (DIO2, GPX1, GPX4, SELENOI, SELENON, SELENOS, TXNRD1 and TXNRD3) and five were down-expressed (DIO1, GPX2, GPX3, SELENOP and SELENOW) in TNBC compared to all other “non-TNBC” breast cancer subtypes." (PMID 35158912, 2022).
selenium deficiency (6 papers, 2012 to 2025). A nutritional deficiency disease resulting from inadequate selenium levels in the body, which can lead to impaired function of selenoproteins essential for antioxidant defense and thyroid hormone metabolism. "Selenop and Dio1 which rank in the middle of the selenoprotein hierarchy showed a moderate response to selenium deficiency being more pronounced in females than in males." (PMID 41401733, 2025). "As recently demonstrated by a rodent model of dietary intervention, iodine-deficiency primary affects thyroid functions and activities, while other factors (here selenium-deficiency) lead to isolated Dio1 and Dehal1 changes in target organs." (PMID 35387426, 2022). "Decreased Dio1 activity is observed in older age, certain medications (e.g., propranolol and propylthiohuracil), and those with a selenium deficiency." (PMID 34098145, 2021). "In line with this notion, the observed upregulation of TH transporters in the -Se/-I-supplied group appears to be a combinatory effect induced by low T4 levels in response to low iodine and reduced local Dio1 activity due to selenium deficiency." (PMID 34836027, 2021). "DIO1 as a selenoprotein has also been discovered to be protective against iodine deficiency when its activity is reduced with selenium deficiency." (PMID 24352087, 2013). "Interestingly, zinc deficiency modulated selenoprotein expression and reduced Selenow and Dio1 expression to an extent comparable to selenium deficiency." (PMID 41401733, 2025). "As Dio1 mRNA levels were not affected this is most probably a translational effect due to limited selenium availability and is in accordance with literature describing the organ-specific effects of severe selenium deficiency." (PMID 34836027, 2021).
depression (5 papers, 2023 to 2024). "There is evidence that a DIO1 variant, rs11206244, which is in tight linkage disequilibrium with rs2235544, is associated with lifetime major depression." (PMID 38355654, 2024). "DIO1 and DIO3 may participate in the mechanism of depression risk during alcohol consumption; after three months of reduced alcohol usage, DIO1 activity increased and reached the normal range, while DIO3 activity was inhibited." (PMID 37834806, 2023). "Other research reported that a decreased level of TSH was associated with a higher level of IL8 in individuals with depression, a population with increased risk for diabetes; this relationship may be linked to the activity of DIO1 and to specific variants of phosphodiesterase and the TSH-receptor." (PMID 39525855, 2024). "Both White and African persons have several genotypic variants including one in the 3 ′UTR of DIO1 (rs11206244) and changed FT4 levels are linked to lifelong serious depression." (PMID 36811059, 2023). "Mutations of the 3′ UTR variant of DiO1 (rs11206244) have been associated with altered free thyroxine (FT4) levels in both White and African American subjects, as well as with lifetime major depressive disorder in White female subjects, in particular those from high-risk cohorts." (PMID 37511721, 2023).
depressive disorder (5 papers, 2023 to 2025). A melancholy feeling of sadness and despair. "In addition, the DiO1, DiO2 Thr92Ala, and SLCO1C1 mutation SNPs show a high sensitivity and specificity in differentiating depressive disorder from BSD." (PMID 37511721, 2023). "Recent findings further highlight that SNPs in DIO1, DIO2 and SLCO1C1 showed high sensitivity and specificity in differentiating depressive disorder from BD, emphasising the role of genetic variations in TH pathways in delineating between different mood disorders." (PMID 40586856, 2025).
Hepatic steatosis (4 papers, 2023 to 2025). Steatosis is a term used to denote lipid accumulation within hepatocytes. "Knockdown of liver Dio1 favored the development of fatty liver disease (NAFLD/MASLD) due to reduced fatty acid oxidation." (PMID 38182610, 2024).
clear cell renal cell carcinoma (3 papers, 2011 to 2024). "Both microRNAs are markedly overexpressed in clear cell renal cancer and possibly account for loss of DIO1 expression in tumor." (PMID 21912701, 2011). "DIO1 expression is reduced in the most common type of kidney neoplasia, clear cell Renal Cell Carcinoma (ccRCC)." (PMID 21912701, 2011). "In previous works we showed decreased expression of DIO1 mRNA and activity, and disturbed alternative splicing of DIO1 pre-mRNA in clear cell Renal Cell Carcinoma (ccRCC)." (PMID 21912701, 2011). "Our observation that DIO1 expression is disturbed is supported by previous reports in different types of cancer, with a similar reduced expression in papillary thyroid carcinoma, thyroid adenoma, lung cancer, hepatic cancer, and clear cell renal cell carcinoma." (PMID 38429887, 2024). "Thus, GPX3 and DIO1 expression may serve a potential diagnostic indicator in KIRC, representing a potential mechanism of sufficient selenium status in the human body protecting against renal clear cell carcinoma genesis." (PMID 32316597, 2020).
diabetes (3 papers, 2020 to 2024). "Among them, 89 upregulated and 24 downregulated DEGs were found to be associated with diabetes progression (e.g., Ctrb1, Cpa2, and Insig1) and diabetes (e.g., Car3, Dio1, and Mup5), respectively." (PMID 33329383, 2020). "In this regard, a 50–60% decrease in hepatic Dio1 was observed in experimental diabetes in rats." (PMID 34445217, 2021).
hepatocellular carcinoma (3 papers, 2014 to 2023). A malignant tumor that arises from hepatocytes. "In hepatocellular carcinoma, reduced expression of Dio1 was observed both in the tumors and in the surrounding cirrhotic tissue, although results have been inconsistent." (PMID 36892852, 2023). "Upstream of Dio1, the oncogene astrocyte elevated gene-1 (Mtda) and the transcription factor forkhead box A1 (Foxa1) play an important role in reducing Dio1 expression in hepatocellular carcinoma." (PMID 36892852, 2023). "In liver disease, decreased Dio1 expression and activity has been observed in inflammation, fibrosis, and hepatocellular carcinoma, whereas increased Dio3 has been observed in fibrosis." (PMID 36892852, 2023). "In another in vitro study, T3 increased the mRNA level of Dio1 by 76 ± 17% and the activity of Dio1 by 101 ± 30% in rat hepatoma cells." (PMID 36605939, 2022). "Currently, it is unknown whether direct modulation of Dio1 expression alters tumorigenesis in hepatocellular carcinoma." (PMID 36892852, 2023). "Hepatocellular carcinoma cell lines (HepG2) were transfected with small interfering ribonucleic acid (siRNA) specific for deiodinase type 1 (DIO1) and cultured with or without uremic toxins." (PMID 25174507, 2014).
liver disease (3 papers, 2023 to 2025). "This is of interest due to the now-known Dio1 polymorphisms and mutations affecting a significant portion of the population which may alter the course of liver disease." (PMID 36892852, 2023). "They found in both a test and validation cohort of human NAFLD, a decreased fT3/rT3 ratio during advanced liver disease accompanied by decreased DIO1 and increased DIO3 protein." (PMID 36892852, 2023). "Of note, hepatic DIO1 is a key converting enzyme required for efficient conversion of FT4 to FT3, and it is known that hepatic DIO1 expression is reduced in acute non-hepatic diseases." (PMID 36755907, 2023).
renal carcinoma (3 papers, 2011 to 2022). A carcinoma arising from the epithelium of the renal parenchyma or the renal pelvis. "miR-224 mediates loss of DIO1 in renal cancer, what results in decreased intratumoral T3 concentration." (PMID 21912701, 2011). "Binding of miR-224 to DIO1 3′UTR results in downregulation of endogenous DIO1 expression in renal cancer cells." (PMID 21912701, 2011). "MiR-224-5p, the most up-regulated miR in nodules (+254 fold vs. controls), was recently shown to target deiodinase 1 (Dio1), an enzyme expressed in the liver and kidney and required for the conversion of T4 to T3 in rat hepatocytes and human renal carcinoma cells." (PMID 36203462, 2022).
thyroid cancer (3 papers, 2015 to 2025). "Eleven of 18 BRAFV600E-specific genes were previously reported as related to thyroid cancer, with 6 documented as associated with BRAF mutation (DCSTAMP, MET, FN1, DIO1, EPHA2, and ERBB3)." (PMID 26625260, 2015). "It is observed that DIO1 was downregulated in four cancer types: Kidney Chromophobe (KICH), Kidney Renal Clear Cell Carcinoma (KIRC), Kidney Renal Papillary Cell Carcinoma (KIRP), and Thyroid carcinoma (THCA)." (PMID 32316597, 2020).
metastatic tumor (2 papers, 2024 to 2025). "In metastatic tumors, significant reductions were observed in DIO1 activity (11-fold), TFF3 gene expression (8-fold), TPO expression (4-fold), and SLC26A7 expression (2.6-fold)." (PMID 40650194, 2025). "We have further demonstrated that the expression of DIO1 is maintained at a relatively low level, not only in the primary and metastatic tumor sites but also in the pre‐malignant fallopian tube regions." (PMID 38429887, 2024). "The limited expression of DIO1 throughout HGSOC evolution, from the early precursor FT lesion, to the primary and metastatic tumor sites, strongly implies that the enzyme downregulation may facilitate disease progression." (PMID 38429887, 2024).
Obesity (2 papers, 2021 to 2023). Accumulation of substantial excess body fat. "Xia and colleagues observed decreased Dio1 activity, Dio1 mRNA, and DIO1 protein in obesity-prone mice after 7 weeks of high-fat diet opposed to increased Dio1 expression in obesity-resistant mice." (PMID 36892852, 2023).
papillary thyroid carcinoma (2 papers, 2011 to 2024). "For instance, DIO1 mRNA and activity are decreased in papillary thyroid carcinoma and increased in follicular adenoma and follicular thyroid carcinoma." (PMID 21912701, 2011).